ERO1A (endoplasmic reticulum oxidoreductase 1 alpha)
Diseases named in the same sentence as ERO1A in open-access papers (continued):
Sharing a sentence is not in itself a finding about the gene and the disease.
cardiac hypertrophy (2 papers, 2017 to 2022). "Under conditions of increased ER stress such as cardiac hypertrophy, upregulation of ERO1α removes ERp44 from the RyR2 channel complex, contributing to spontaneous Ca2+ release from the SR and increased risk for Ca2+-dependent arrhythmias." (PMID 36425292, 2022). "We have recently demonstrated the antiarrhythmic effects of inhibiting ERO1α, an oxidoreductase downstream of PERK and CHOP in a model of cardiac hypertrophy." (PMID 36425292, 2022).
Cerebral ischemia (2 papers, 2015 to 2020). Restriction of arterial blood supply to the brain associated with insufficient oxygenation to support the metabolic requirements of the tissue. "In our study, global cerebral ischemia was associated with increased transcriptional levels of CHOP and Ero1-α." (PMID 25989620, 2015). "Global cerebral ischemia induced upregulation of CHOP and endoplasmic reticulum oxidoreductin-α (Ero1-α) in rat hippocampi, while induced hypothermia (31°C) attenuates CHOP and augments Ero1-α expression in the PC12 cell line." (PMID 33381263, 2020).
Hypoglycemia (2 papers, 2017 to 2018). A decreased concentration of glucose in the blood. "Interestingly, ERO1α interacts with ERp44, a negative regulator of IP3Rs and ERO1α expression is independently regulated by both hypoxia and hypoglycemia, two known microenvironmental factors associated with cancer development." (PMID 29491398, 2018). "The oxireductase endoplasmic reticulum oxidoreductin 1-α ERO1-α was strongly upregulated by hypoxia and independently by hypoglycemia, two known accompaniments of tumors." (PMID 28881752, 2017).
laryngeal squamous cell carcinoma (2 papers, 2024 to 2025). A squamous cell carcinoma that arises from the larynx. "Similarly, in organoid models of prostate cancer and laryngeal squamous cell carcinoma, activating the androgen receptor (AR)/GPX4 axis and inhibiting endoplasmic reticulum oxidoreductase 1 alpha (ERO1α) have both led to improved therapeutic outcomes." (PMID 40427552, 2025).
liver cancer (2 papers, 2023). An epithelial or non-epithelial malignant neoplasm that arises from the liver. "In liver cancer cell lines overexpressing NEAT1v1, these target genes, except for ERO1α, were downregulated." (PMID 36826016, 2023).
Stroke (2 papers, 2015 to 2025). Sudden impairment of blood flow to a part of the brain due to occlusion or rupture of an artery to the brain. "Our results draw attention to the potential effect of hypothermia on the UPR and future studies of CHOP and Ero1-α regulation at the protein level will further substantiate their feasibility as drug targets in stroke treatment." (PMID 25989620, 2015).
Viral Infections (2 papers, 2016 to 2018). "Despite a tremendous significance of polyamines and Ero1α for normal cell growth, their interplay with viral infections remains poorly studied." (PMID 29673197, 2018). "Data on the status of Ero1α in human viral infections are scarce and limited to just two human and one plant virus." (PMID 29673197, 2018).
Alzheimer disease (1 paper, 2025). A progressive, neurodegenerative disease characterized by loss of function and death of nerve cells in several areas of the brain leading to loss of cognitive function such as memory and language. "In neurodegenerative diseases such as Parkinson’s disease and Alzheimer’s disease, the ER protein misfolding under excessive stress can activate ERO1α, exacerbating cell oxidative stress and further damage to neurons." (PMID 41333024, 2025). "No published studies have focused on the contributions of ERO1α to the pathogenesis of Alzheimer’s disease." (PMID 41333024, 2025).
COVID-19 (1 paper, 2022). A disease caused by infection with severe acute respiratory syndrome coronavirus 2. "A total of 6 hub genes were obtained, including: LDHA, TRPA1, PKP2, FBN2, ERO1A, FSCN1, all of which are risk factors for LUAD/COVID-19." (PMID 36157452, 2022).
dyslipidemia (1 paper, 2017). "In summary, chronic stress–induced ROS become intra-ER ROS that cause PDI/ERO-1α uncoupling, which results in ER stress and apoB aggregation-associated hepatic dyslipidemia." (PMID 28747775, 2017).
endothelial dysfunction (1 paper, 2023). In vascular diseases, endothelial dysfunction is a systemic pathological state of the endothelium (the inner lining of blood vessels) and can be broadly defined as an imbalance between vasodilating and vasoconstricting substances produced by (or acting on) the endothelium. "In summary, these results suggested that Ero1α knockdown effectively rescued endothelial dysfunction and inhibited endothelial apoptosis and inflammation in SIRT6 deficiency under OGD/R conditions." (PMID 37598403, 2023). "We found that SIRT6 inhibited HIF1α transcriptional activity by antagonizing p300 acetylation of H3K9 at the Ero1α promoter, thereby suppressing Ero1α expression and augmentation of ERS‐induced endothelial dysfunction." (PMID 37598403, 2023). "Endoplasmic reticulum oxidase 1 alpha (Ero1α) expression is enhanced during ischemia‒reperfusion due to increased p300‐mediated H3K9Ac modification, resulting in increased endoplasmic reticulum stress (ERS) and endothelial dysfunctions." (PMID 37598403, 2023). "Additionally, Ero1α silencing could restore the protein levels of VE‐cadherin, p‐eNOS and eNOS in SIRT6‐deficient HUVECs under OGD/R conditions, which suggested that inhibiting Ero1α could substantially ameliorate OGD/R‐induced endothelial dysfunction in the absence of SIRT6." (PMID 37598403, 2023).
hyperglycaemia (1 paper, 2018). "In the present study, we observed less expression of PDI and ERO1α in diabetic rats when compared with healthy rats, suggesting that hyperglycaemia could impair oxidative protein folding in the ER." (PMID 29614832, 2018).
Insulin resistance (1 paper, 2025). Increased resistance towards insulin, that is, diminished effectiveness of insulin in reducing blood glucose levels. "The covalent binding between ERp44 and ERO1α may be controlled by modulating ERp44 SUMOylation in adipocytes which provides a viable strategy for addressing obesity and insulin resistance." (PMID 41333024, 2025).
ischemia (1 paper, 2015). A hypoperfusion of the BLOOD through an organ or tissue caused by a PATHOLOGIC CONSTRICTION or obstruction of its BLOOD VESSELS, or an absence of BLOOD CIRCULATION. "As a result of ischemia, a significant increase in expression of CHOP and Ero1-α was observed after three, six and twelve hours of reperfusion following global ischemia." (PMID 25989620, 2015). "Whereas high CHOP expression was maintained throughout the study period, ERo1-α peaked at 3 to 6 h (ischemia) and 6 h (hypoxia), respectively." (PMID 25989620, 2015).
mesothelioma (1 paper, 2022). A usually malignant and aggressive neoplasm of the mesothelium which is often associated with exposure to asbestos. "In this context, the treatment of mesothelioma REN cells with BOLD-100 induces the doubling of ERO1α protein level." (PMID 36077664, 2022).
neuroblastoma (1 paper, 2017). Neuroblastoma (NB) is the most common solid, extracranial childhood tumor. "We additionally show that chronic thapsigargin treatment triggers an ectopic expression of CHOP that correlates with calnexin deficiency and ERO1α excess in SH-SY5Y neuroblastoma cells." (PMID 29170452, 2017).
Parkinson disease (1 paper, 2025). A progressive degenerative disorder of the central nervous system characterized by loss of dopamine producing neurons in the substantia nigra and the presence of Lewy bodies in the substantia nigra and locus coeruleus. "In the 1-methyl-4-phenylpyridinium (MPP+) model of Parkinson’s disease, inhibition of PDI or inhibition of ERO1α by EN460 (IC50 of 1.9 μM) can prevent accumulation of α-synuclein and MPP+ neurotoxicity in the ER." (PMID 41333024, 2025).
pheochromocytoma (1 paper, 2015). "The gene expression of CHOP and Ero1-α was measured using Quantitative-PCR (Q-PCR) in rat hippocampi following global cerebral ischemia, and in hypoxic pheochromocytoma cells during normothermic (37 °C) and hypothermic (31 °C) conditions." (PMID 25989620, 2015).
Thiamine deficiency (1 paper, 2021). Thiamine deficiency is a condition that occurs due to not enough thiamine (vitamin B1). "The thiamine-dependent downregulation of the ERO1A level, observed independently of daytime, is of particular interest also in view of neurodegeneration-causing events, which are stimulated by thiamine deficiency and decreased by thiamine addition." (PMID 34360775, 2021).
tumor (61 papers, 2006 to 2026). "ERO1A expression was positively correlated with the density of infiltrating CD163+ tumor-associated macrophages (TAMs) in ccRCC." (PMID 41809819, 2026). "The expression of ERO1A significantly correlates with that of VEGF and other HIF1-dependent angiogenic factors, suggesting a close association between ERO1A, multiple angiogenic regulators, and angiogenesis in this tumor type." (PMID 39962052, 2025). "This was further supported by the fact that depletion of tumor-associated PMN-MDSCs in ERO1α+ 4T1 cells inhibited tumor growth compared to control." (PMID 41226317, 2025). "Elevated ERO1α levels are associated with increased tumor aggressiveness, metastasis, and poor clinical outcomes." (PMID 41226317, 2025). "Functionally, ERO1α promoted proliferation, angiogenesis, and tumor growth in Tsc2-deficient cells, both in vitro and in vivo." (PMID 41226317, 2025). "Overexpression of ERO1α is widely reported across various cancer types and often associated with poor clinical outcomes, highlighting its role in tumor survival." (PMID 41226317, 2025). "ACSS1 and ERO1A are highly expressed in tumors and can promote tumor progression metabolic changes associated with cancer cell survival." (PMID 37101691, 2023). "Since Ero1aKO tumor cells were associated with apoptotic signaling pathways in response to ER stress, we interrogated the role of ERO1A in the cell survival of tumors undergoing ER stress." (PMID 37769655, 2023). "As expected, the levels of protein expression of the three high-risk genes (ITGB4, CDKN2A, and ERO1A) were demonstrably higher in tumour tissues with more intense antibody staining and a greater proportion of stained cells." (PMID 32238163, 2020). "It is possible that ERO1α functions predominantly in the structural formation of various molecules under hypoxic conditions, strengthening the causal relationship between increased expression of ERO1α and tumour progression." (PMID 31142270, 2019). "Accordingly, when transferred into a mouse xenograft model, ERO1α-deficient tumor cells exhibited severe growth restriction and negligible disease progression in vivo." (PMID 31666928, 2019). "High levels of ERO1α were significantly associated with tumor vascular invasion (P = 0.003), tumor pathologic stage (P = 0.009), and tumor TNM stage (P = 0.034)." (PMID 30377291, 2018). "MAMs perform microzones of anchoring enzymes that maintain oxidative homeostasis, such as endoplasmic reticulum oxidoreductase-1 alpha (ERO-1α), with which overexpression in tumor tissue is associated with poor prognosis." (PMID 30149660, 2018). "Together, these data confirmed that ERO1α-deficient PDA cells exhibit impaired tumor development in vitro, so we next performed xenograft experiments in Ncr-nude mice to determine whether these cells also displayed reduced oncogenic potential in vivo." (PMID 31666928, 2019). "However, the clinical relevance of ERO1α and the molecular mechanisms underlying tumor progression have yet to be determined in HCC." (PMID 30377291, 2018). "In the KO-cell groups, the tumour was engrafted, but the tumourigenicity here was markedly diminished as compared with that of the WT or mock control group, which suggested that ERO1α deficiency reduced the tumourigenicity of the cancer cells." (PMID 28839225, 2017). "Elevated ERO1A, OSBPL3 and IFI44L protein expression in tumor tissues may cause patients’ median survival time 18.83%-44.07% (ERO1A:44.07%, OSBPL3: 18.83%and IFI44L, 42.37%) shorter than patients who without." (PMID 28881752, 2017). "The variability in ERO1α upregulation across cell lines suggests that its response is influenced by specific hypoxia-related factors and the tumor microenvironment." (PMID 41226317, 2025). "ERO1α confers a faster growth rate and a more aggressive phenotype to tumor cells by promoting angiogenesis and differentiation of immunosuppressive cells and inducing an immunosuppressive TME, leading to immune cell dysfunction." (PMID 40616124, 2025).
tumor (continued). "By regulating oxidative folding, ERS, Vascular endothelial growth factor (VEGFin hypoxia, ERO1α promotes tumor growth, angiogenesis and metastasis and chemoresistance)." (PMID 41333024, 2025). "Beyond its effects on cell migration and tumor growth, ERO1α is also involved in protein folding and secretion under hypoxia." (PMID 41226317, 2025). "Taken together, these findings suggest that ERO1α is not only involved in VEGF-A secretion but also influences tumor behavior by regulating angiogenesis and metastasis." (PMID 41226317, 2025). "Recently, ERO1α has gained attention for its upregulation in several cancer types, particularly in hypoxic and highly secretory tumor environments." (PMID 41226317, 2025). "They proposed that hypoxia, a common feature of solid tumors, enhances VEGF-A release through ERO1α, reinforcing its role in tumor angiogenesis and metastasis." (PMID 41226317, 2025). "Another mechanism on how ERO1α expression can modulate anti-tumor immunity is via upregulation of Programmed Cell Death Ligand 1 (PD-L1)." (PMID 41226317, 2025). "This suggests that ERO1α expression is inducible in primitive luminal cancer stem-like cells, thereby integrating stemness, epigenetic control, and tumor adaptation." (PMID 41226317, 2025). "Altogether, these results highlight the importance of ERO1α in facilitating anti-tumor immunity mainly via two mechanisms: recruitment of immunosuppressive PMN-MDSC cells and increased production of immune checkpoint protein PD-L1." (PMID 41226317, 2025). "Together, these mechanistic insights emphasize that ERO1α contributes not only to tumor cell survival and angiogenesis but also to resistance against ferroptosis and immune attack." (PMID 41226317, 2025). "In parallel, ERO1α has also been shown to modulate the tumor immune microenvironment—specifically, it enhances the oxidative folding and secretion of immunosuppressive cytokines such as G-CSF, CXCL1, and CXCL2, which are instrumental in recruiting PMN-MDSCs." (PMID 41226317, 2025). "As such, ERO1α represents a promising target for combinatorial therapies aimed at enhancing ferroptosis sensitivity and reversing tumor immune suppression." (PMID 41226317, 2025). "Beyond its well-characterized function in oxidative protein folding, ERO1α contributes to several tumor-promoting processes, including hypoxia adaptation, ER stress mitigation, and angiogenesis through proper VEGF-A maturation." (PMID 41226317, 2025). "This dual relationship underscores ERO1α’s critical role in supporting tumor cell survival, angiogenesis, and metabolic adaptation." (PMID 41226317, 2025). "Compared to well-established biomarkers, this makes ERO1α a relatively new target in oncology, with its precise contribution to tumor progression and therapy resistance still underexplored." (PMID 41226317, 2025). "Since ERO1α mediates ferroptosis resistance and tumor growth induced by mTORC1 activation, our next goal is to search for downstream effectors of the mTORC1/ERO1α pathway." (PMID 38610018, 2024). "In this report, we found that ablating ERO1A expression was a determinant of clonogenicity, tumor sphere formation, spheroid growth and growth in vivo, as well as response to Osimertinib." (PMID 39496753, 2024). "We also illustrated that elevated ERO1α expression contributes to tumor progression driven by mTORC1 activation." (PMID 38610018, 2024). "Endoplasmic reticulum oxidoreductin 1-α (ERO1A) plays a crucial role as a regulator of protein disulfide isomerase, and recent research has suggested that both protein disulfide isomerase and ERO1A are significant factors in tumor prognosis." (PMID 38319721, 2024). "In contrast, the results of a xenograft assay with ERO1α-overexpressing Tsc2 + / + MEFs showed that overexpression of ERO1α promotes tumor cell proliferation and angiogenesis in vivo." (PMID 38610018, 2024).